CCL21 (C-C motif chemokine ligand 21)
Diseases named in the same sentence as CCL21 in open-access papers (continued):
Sharing a sentence is not in itself a finding about the gene and the disease.
melanoma (continued). "Of note, malignant melanoma cells also express CCL21, which has been recently revealed to convey a significant, alternative mechanism for tumor progression." (PMID 24212647, 2011). "In a previous study, Gr1+ polymorphonuclear cells appeared to invade the medulla, upper cortex and capsule of transplanted melanoma-TDLN with decreased CCL21 expression." (PMID 21811640, 2011). "Novel engineered protein antagonists of CCR7 that bind CCL21 have been shown to block CCR7-mediated migration of melanoma cells in vitro and in vivo, raising the potential for therapeutically active CCR7 antagonists in patient care." (PMID 24212647, 2011). "In the autochthonous Amela-melanoma model, splenic reduction in CCL19 and CCL21 transcripts was associated with loss of gp38+ FRC, generating a phenotype similar to that of plt/plt mice with a defect in recruitment of naïve TL." (PMID 21811640, 2011). "Melanoma cells with relatively higher expression of CCR7 are more migratory in vitro when exposed to CCL21." (PMID 24212610, 2010). "•The host-derived CCL21-Ser regulates Treg-mediated anti-melanoma immunity." (PMID 37664721, 2023). "Overall, 89%, 92%, 82%, and 50% of patients failed to display detectable serum levels of BAFF/TNFSF13B, CX3CL1, LTα, and CCL21 (defined as < 2 pg/ml, < 0.5 pg/ml, < 1 pg/ml and <7 pg/ml for the respective analytes) amongst an initial cohort of 78 melanoma patients evaluated." (PMID 37435077, 2023). "In addition, the activated CD8+ T cells recognizing TRP-2 were significantly increased in Ccl21a-KO tumors than in WT tumors, suggesting that host-derived CCL21-Ser has a suppressive effect on anti-melanoma immunity." (PMID 37664721, 2023). "The blockade of CCL21/CCR7 axis may collectively serve as a strategy for lymphatic metastasis in some melanoma after chemotherapy." (PMID 35280672, 2022). "However, various clinical trials use CCL21 gene modified dendritic cells (DCs-adenovirus CCL21) as anticancer vaccination strategies in lung cancer or melanoma (NCT00601094, NCT01433172, NCT01574222, NCT03546361 and NCT00798629)." (PMID 35211124, 2022). "A role for VEGF-C in inducing CCL21/CCR7-mediated lymphangiogenesis of melanoma cells was noted and a low percentage of melanoma cells expressed the immune checkpoint ligands, PD-L1 and galectin-9, resulting in cancer stem cell characteristics and increased metastasis." (PMID 35203305, 2022). "In addition, increased VEGF-C and CCL21 staining was found in CCR7-expressing melanoma relative to control melanoma, further demonstrating a role for VEGF-C in lymphangiogenesis in mice." (PMID 35203305, 2022). "GBM and melanoma induced remodeling of meningeal lymphatic vessels mainly through the VEGF-C/CCL21 signaling pathway, which also illustrated the role of meningeal lymphatic tracts in the tumor microenvironment of the brain tumors and provided new targets for brain tumor treatment." (PMID 35359624, 2022). "The CCL21/CCR7 signalling axis might be a superior target compared with other treatment strategies for treating patients with melanoma and lymph node metastasis." (PMID 35280672, 2022). "In summary, our data indicated that PTX treatment could increase lymphatic metastasis of B16F10 melanoma cells upon chemotherapy via the enhancement of the CCL21/CCR7 axis." (PMID 35280672, 2022). "It is unclear whether CCL21/CCR7 signalling axis also plays a crucial role in promoting melanoma lymphatic metastasis after other chemotherapeutic drugs." (PMID 35280672, 2022). "The current study investigated whether CCL21/CCR7 axis involves lymphatic metastasis of melanoma after chemotherapy." (PMID 35280672, 2022). "Intratumoral injection of CCL21 facilitated lymphocyte infiltration into pancreatic tumors, and targeting lymphotoxin-α can induce lymphocyte infiltration and lymphoid-like tissue formation in B16 melanoma." (PMID 34394083, 2021).
melanoma (continued). "In mice, overexpression of CCR7 in B16 melanoma cells increased metastasis to the lymph node and neutralizing its ligand, CCL21, using a specific antibody blocked this metastatic process, highlighting the importance of this CCR7/CCL21 axis in the metastasis to the regional lymph node." (PMID 30420855, 2018). "However, the exact mechanism of CCL21/CCR7 signalling axis-induced lymphatic metastasis in melanoma after PTX treatment remains unclear." (PMID 35280672, 2022). "In vivo studies using B16 melanoma cells injected into nude mice showed that CCR7-expressing melanoma cells migrated more efficiently to lymphatic tissue in response to CCL21 that could be inhibited by a CCL21 neutralizing antibody." (PMID 35203305, 2022). "Similarly, CCL21/CCR7 pair seems to play an important role in the lymphangiogenesis associated with pancreatic cancer and – due to its chemotactic properties – this chemokine axis is involved in the lymphatic spread of melanoma cells." (PMID 25744065, 2015). "Another possible immune signal that may be lost during melanoma development is CCL21." (PMID 24762633, 2014). "Melanoma expressing high CCL21 level by lentivirus (~0.18 pg/1000 cells in vitro) displayed more aggressive growth at day 9 and exhibited immunosuppressive microenvironment, which were absent in melanoma with low levels of CCL21 caused by shRNA knockdown." (PMID 24810425, 2014). "For example, treatment of melanoma with the STING agonist ADU S-100 increased the production of several TLS-inducible factors, such as CCL19, CCL21, Lt-α, Lt-β, and Light, and inhibited melanoma growth." (PMID 40038799, 2025). "The major chemokine/chemokine receptor interactions occurring in melanoma development and progression include the CXCR4/CXCR7/CXCL12, CXCR3/CXCL9,10,11, CXCR1,2/CXCL8, CCR2/CCL2, CCR4/CCL17,22, CCR5/CCL5, CCR7/CCL21 and CCR10/CCL27 axes." (PMID 37170733, 2023). "In the present study we apply, for the first time, the CCL21+ICAM1 based SIN technology, on human TIL, derived from melanoma patients." (PMID 36937426, 2023). "Extensive work in cancer immunotherapy has shown that the CCL21/CCR7 expression axis promotes growth and metastasis in a variety of tumor types, including melanoma, breast, thyroid, colon, head, and neck cancers." (PMID 37426658, 2023). "In vitro experiments showed that A375 cells derived from a malignant melanoma expressed CCR7, producing chemotaxis towards CCL21, which was prevented by CCL21 neutralizing antibodies, such as B16 melanoma cells." (PMID 35203305, 2022). "More recently, using the B16 melanoma model, VEGF-C-induced CCL21/CCR7-mediated lymphangiogenesis that promoted the entry of naïve T cells into melanomas and thereby, enhanced the activity of immunotherapy." (PMID 35203305, 2022). "In CCR7-expressing melanoma cells, VEGF-C and CCL21 were expressed by lymphatic vessels and enhanced lymph node metastasis compared to non-CCR7-expressing control tumors." (PMID 35203305, 2022). "A number of identified molecules, including TNFRSF13B, LAG3, NRP1, ENTPD1, NT5E, CCL21, and CCR7, can serve as future therapeutic targets in the treatment of melanoma." (PMID 34159752, 2021). "Melanoma cells exploit this same chemokine axis by upregulating CCR7 expression, enabling migration towards CCL21-producing LECs." (PMID 34830780, 2021). "A number of identified molecules including TNFRSF13B, LAG3, NRP1, ENTPD1, NT5E, CCL21, and CCR7 can serve as future therapeutic targets in melanoma treatment." (PMID 34159752, 2021). "In spontaneous and orthotopic models of melanoma, TDLN FRCs proliferated, but produced less IL-7 and CCL21, which are critical for T cell survival and guidance, respectively." (PMID 29527513, 2018). "The mature adipocyte-stimulated expression of CCL19 and CCL21 in lymphatic endothelial cell, and expression of their receptor CCR7 in melanoma cells, which contributes to increased lymph node metastasis of melanoma in high-fat diet-fed mice." (PMID 29137230, 2017).
melanoma (continued). "CCL21 is constitutively expressed by the lymphatics and its receptor CCR7 is expressed by melanoma and breast cancer cells." (PMID 28036019, 2016). "Among them, C-C chemokine ligand 21/chemokine receptor 7 (CCL21/CCR7) pair promotes growth and metastasis of many tumor types including melanomas, breast, thyroid, colon, head, and neck cancers." (PMID 25744065, 2015). "Most chemokines were expressed intracellularly in all melanoma cell lines (CXCL9, CXCL11, CXCL12, CCL19, CCL21 and CCL27)." (PMID 24559071, 2014). "Fusing this gene construct with plasmid DNA coding for CCL21 (pCCL21-3P-Fc), the investigators introduced this construct into the B16FO melanoma cell line to create a genetically modified tumor vaccine." (PMID 24967094, 2013). "Despite the correlation of the CCR7/CCL21 axis with melanoma metastasis to the lymph nodes, there are currently no inhibitors on the market to inhibit the downstream effects of this axis." (PMID 37170733, 2023). "In the study reported here, we have tested the effect of the CCL21+ICAM1 SIN, on the expansion and cytotoxic phenotype of Tumor Infiltrating Lymphocytes (TIL) from melanoma patients, following activation with immobilized anti-CD3/CD28 stimulation, or commercial activation beads." (PMID 36937426, 2023). "Interestingly, in melanoma clinical datasets, PAK4 expression levels negatively correlate with the presence of CCL21, the ligand for CCR7 expressed in CD103+ DCs." (PMID 36588582, 2022). "CCL21 and CCR7 were both produced by melanoma tissue promoting an immunotolerant phenotype." (PMID 35203305, 2022). "Nevertheless, the combination therapy targeting the CCL21/CCR7 axis and chemotherapy might provide a new direction for melanoma B16F10." (PMID 35280672, 2022). "Analysis of several melanoma cell lines and tumor samples showed heterogeneous CCR7 expression as measured by quantitative real-time reverse transcriptase PCR, with CCR7 levels corresponding to CCL21 migration." (PMID 35203305, 2022). "Furthermore, cancer-associated adipocytes led to the upregulation of chemokine ligands (CCLs)—CCL19 and CCL21—levels in the lymph nodes, as well as increased chemokine receptor 7 (CCR7) expression in melanoma cells." (PMID 33430277, 2021). "Low level CCL21 release (~120 pg/5 × 105 cells/48 h in vitro) driven by CMV promoter from melanoma led to smaller, but not rejected, tumor growth after 3 weeks." (PMID 24810425, 2014). "Forced expression of CCL21 in melanoma cells caused an increase of NK and CD8+ T cell infiltrate resulting in a bolstered immune response when compared to melanomas lacking CCL21." (PMID 24762633, 2014). "Furthermore, intra-tumoral expression of CCL21 boosted CTL responses after DNA vaccination of mice and induced regression of B16 melanomas." (PMID 23874342, 2013). "Interactions between CXCL12 and CCL21, chemokines produced by lymph nodes and the CXCR7 and CXCR4 chemokine receptors expressed on melanoma cells, may have similar roles in mediating lymph node metastasis." (PMID 24212610, 2010). "There is data that CCL21, which is secreted by endothelial cells lining lymphatic channels, may mediate metastasis though interaction with its receptor, CCR7, on melanoma cells." (PMID 24212610, 2010). "These chemokines, such as CCL21 are used by receptor expressing tumour cells (CCR7 for instance is upregulated in metastatic but not non metastatic melanoma cells) and provide a route out of the primary melanoma to the lymph node." (PMID 20478045, 2010). "Our study does not clarify whether CCL21-Ser supports melanoma growth only in certain genetic backgrounds." (PMID 37664721, 2023). "Given the results presented here, we propose that the CCL21+ICAM1 synthetic niche, which proved to enhance expansion in the murine OVA systems, and elevate the cytotoxic capacity of murine CD8 cells, is capable to reinforce human TIL, derived from melanoma patients." (PMID 36937426, 2023). "•Lack of the host-derived CCL21-Ser reduces B16–F10 melanoma growth." (PMID 37664721, 2023).
melanoma (continued). "When model mice with GBM and melanoma overexpressed VEGF-C, the anti-PD-1/CTLA-4 combination treatment showed a good effect, which was abolished when CCL21/CCR7 blockaded, suggesting an augmented effect of VEGF-C on checkpoint treatment via the CCL21/CCR7 pathway." (PMID 35359624, 2022). "Thus, inhibition of the CCL21/CCR7 axis may be used to counteract chemotherapy-induced metastasis, providing a novel strategy to improve chemotherapeutic treatment for melanoma." (PMID 35280672, 2022). "For instance, when melanoma cells express the receptor CCR7, they are able to migrate along the same ligand gradients as circulating immune cells to enter lymph nodes; however, when CCL21 is expressed by melanoma, immune cell recruitment to the TME via CCL21 gradients is magnified." (PMID 34830780, 2021). "However, we could not find increased levels of CCL21 when using the B16 melanoma tumor model in vivo." (PMID 36588582, 2022). "One group demonstrated that intratumoral injection of ADU S-100, a STING agonist, in a preclinical melanoma model promoted formation of CCL19+, CCL21+, PNAd+ TLS, although these TLS did not contain significant B cell infiltration or GCs." (PMID 38361928, 2024).
lung carcinoma (40 papers, 2008 to 2025). "Intratumoral injection of CCL21 induced DC and T-cell infiltration, causing tumor reduction in a murine lung cancer model." (PMID 33381115, 2020). "The exposure of human H1650 lung carcinoma cells to the CM from siNdst1- or siXylT2-targeted hLEC also resulted in abrogation of CCL21:CCR7 association on the tumor cell surface under similar conditions." (PMID 21172016, 2010). "In a SCID model of lung cancer, however, the direct injection of CCL21 into the TME inhibited angiogenesis and, thereby, tumor growth and metastasis." (PMID 39766038, 2024). "First, we determined the concentrations of CCL21, CD11c+ DCs and EV miR-5193 in malignant pleural effusions (MPEs) from lung cancer patients and found that the EV miR-5193 concentration was positively correlated with the CCL21 and DC concentrations." (PMID 38250037, 2024). "After specific antagonism of the NF-κB pathway with PDTC, CCL21 secretion was significantly reduced, and lung cancer cell metastasis was also reduced in the co-culture system of LECs and lung cancer cells." (PMID 38566083, 2024). "Intratumoral administration of DCs expressing CCL21 in mice induced anti-tumor immunity and markedly suppressed the growth of subcutaneous lung cancer, suggesting the benefit of CCL21 expression in DC-based cancer immunotherapy." (PMID 37664721, 2023). "In a clinical trial, DCs transduced with CCL21 using an adenoviral vector (Ad-CCL21-DC) were administrated to patients with lung cancer who had low infiltration of CD8+ T cells and were resistant to PD-1 therapy to attract T cells and DCs." (PMID 35806328, 2022). "One of the phase I trials is studying the side effects and optimal dose of autologous DC‐adenovirus CCL21 vaccine combined with intravenous pembrolizumab and seeing how well they work in treating patients with stage IV nonsmall cell lung cancer (NCT03546361)." (PMID 35702353, 2022). "In a previous study, we demonstrated that CCL21-DC Tumor Ag vaccine combined with PD-1 blockade leads to tumor eradication in the K-Ras G12Dp53 null model of lung cancer." (PMID 33167311, 2020). "On the other hand, cigarette smoking has been shown to increase blood and bronchoalveolar lavage fluid levels of the CCR7 ligands CCL19 and CCL21, thereby contributing to migration of lung cancer cells." (PMID 32961854, 2020). "We report that PD-1 immune checkpoint blockade combined with CCL21-DC tumor Ag vaccine eradicates tumors and has the potential to augment therapy in lung cancer patients who have low baseline tumor T cell infiltration and do not respond to PD-1 therapy." (PMID 32570793, 2020). "The purpose of this study is to understand the mechanisms of PD-1 blockade combined with therapeutic CCL21-DC tumor Ag vaccination in lung cancer." (PMID 33167311, 2020). "We are currently conducting a phase I clinical trial of CCL21-DC administered intratumorally in patients with advanced-stage lung cancer." (PMID 32570793, 2020). "The activated Erk1/2 signaling not only regulates the expression of chemokines through NF-κB, but also directly participates in CCL21-mediated epithelial-mesenchymal transformation of lung cancer." (PMID 31754081, 2019). "They demonstrated that intratumoral injection of recombinant CCL21 mediated T cell dependent anti-tumor response in a syngeneic immune competent model of lung cancer." (PMID 24810425, 2014). "Dose-escalation studies of intratumoral autologous DC-adenovirus CCL21 vaccine in patients with advanced lung cancer are also currently open." (PMID 24967094, 2013). "Here we describe that vault nanocapsule platform for CCL21 delivery elicits antitumor activity with inhibition of lung cancer growth." (PMID 21559281, 2011). "This study demonstrates that the vault nanocapsule can efficiently deliver CCL21 to sustain antitumor activity and inhibit lung cancer growth." (PMID 21559281, 2011).